MAPRE3 (microtubule associated protein RP/EB family member 3)
Description:
Plus-end tracking protein (+TIP) that binds to the plus-end of microtubules and regulates the dynamics of the microtubule cytoskeleton. Promotes microtubule growth. May be involved in spindle function by stabilizing microtubules and anchoring them at centrosomes. Also acts as a regulator of minus-end microtubule organization: interacts with the complex formed by AKAP9 and PDE4DIP, leading to recruit CAMSAP2 to the Golgi apparatus, thereby tethering non-centrosomal minus-end microtubules to the Golgi, an important step for polarized cell movement. Promotes elongation of CAMSAP2-decorated microtubule stretches on the minus-end of microtubules.
Synonyms: EBF3; EB3; RP3; EBF3-S
Tractability: Small molecule: a structure with a bound ligand is known. PROTAC: ubiquitination databases record sites on it; its protein half-life has been measured.
Gene: Protein-coding gene on chromosome 2 (26,970,633 to 27,027,219, forward strand). Ensembl gene ENSG00000084764.
Subcellular location: Cytoplasm, cytoskeleton
Pathways (Reactome):
Disease: Dengue Virus Attachment and Entry
Gene Ontology:
Molecular function: identical protein binding; protein binding; protein serine/threonine kinase activator activity; protein serine/threonine kinase binding; microtubule binding; microtubule plus-end binding
Biological process: regulation of microtubule polymerization; intracellular protein localization; positive regulation of DNA-templated transcription; protein localization to microtubule; regulation of microtubule polymerization or depolymerization; spindle assembly; behavioral response to cocaine; positive regulation of dendritic spine morphogenesis
Cellular component: mitotic spindle astral microtubule end; cytoplasm; microtubule plus-end; midbody; spindle midzone; cytoskeleton; microtubule; microtubule cytoskeleton; neuron to neuron synapse
Genetic constraint (gnomAD): Loss-of-function variants: 1 observed, 29.16 expected, observed/expected ratio (o/e) 0.0343, 90% interval 0.011 to 0.16. The upper end of that interval is the gene's LOEUF score, 0.16, which puts it in group 1 of 6, group 1 being the genes least tolerant of losing a copy. Missense variants: 191 observed, 333.17 expected, observed/expected ratio (o/e) 0.57, 90% interval 0.51 to 0.65. Synonymous variants: 96 observed, 121.85 expected, observed/expected ratio (o/e) 0.79, 90% interval 0.67 to 0.93.
Homologues: Orthologues: chimpanzee MAPRE3 (100% identical), macaque MAPRE3 (100% identical), dog MAPRE3 (99% identical), mouse Mapre3 (99% identical), pig MAPRE3 (99% identical), rabbit MAPRE3 (99% identical), rat Mapre3 (99% identical), guinea pig MAPRE3 (98% identical), tropical clawed frog mapre3 (85% identical), zebrafish mapre3a (77% identical), zebrafish mapre3b (75% identical), Caenorhabditis elegans ebp-1 (47% identical), and 3 more. Paralogues in human: MAPRE1 (65% identical), MAPRE2 (58% identical).
Diseases named in the same sentence as MAPRE3 in open-access papers:
MAPRE3 is named in the same sentence as 23 diseases in open-access papers, as found by Europe PMC text mining. Sharing a sentence is not in itself a finding about the gene and the disease. The quoted sentences say what the papers report.
melanoma (2 papers, 2017 to 2022). A malignant, usually aggressive tumor composed of atypical, neoplastic melanocytes. "Analyses in primary melanoma and melanoma cell lines indicated that MAPRE3 and EMD mRNA levels were not substantially changed compared to primary normal human epidermal melanocytes (NHEM)." (PMID 28423600, 2017).
colorectal cancer (1 paper, 2018). A primary or metastatic malignant neoplasm that affects the colon or rectum. "The MAPRE3 gene is microtubule associated, with frameshift mutations reported for gastric and colorectal cancers." (PMID 29354286, 2018).
muscle disorders (1 paper, 2020). "To further understand the differential involvement of ADNP in the various muscle disorders, we have also assessed the levels of the ADNP binding proteins EB1 (MAPRE1) and EB3 (MAPRE3)." (PMID 33086621, 2020).
renal oncocytoma (1 paper, 2024). "Expression of biomarkers MAPRE3, ADGRF5, and GPNMB differentiates renal oncocytoma from chromophobe RCC, and PIGR and SOSTDC1 distinguish papillary RCC from MTSCC." (PMID 38703764, 2024).
scrapie (1 paper, 2008). A fatal disease of the nervous system in sheep and goats, characterized by pruritus, debility, and locomotor incoordination. "The third gene encoding a protein named microtubule-associated protein, RP/EB family, member 3 (MAPRE3, EB3), was significantly altered with a threefold increase in expression in the scrapie-infected animals (P = 0.05)." (PMID 18373840, 2008). "The expression of three genes encoding MAPRE3, LOC729073 and DNAJC3 were significantly altered in ileal PP of the scrapie-infected animals as confirmed by real-time PCR." (PMID 18373840, 2008). "Expression of the three genes, MAPRE3, LOC729073 and DNAJC3, were all found significantly altered in ileal PP of scrapie-infected animals." (PMID 18373840, 2008). "The expression of three genes (MAPRE3, LOC729073 and DNAJC3), were found to be significantly altered in scrapie infected lambs (P < 0.05)." (PMID 18373840, 2008).
cancer (8 papers, 2017 to 2024). A tumor composed of atypical neoplastic, often pleomorphic cells that invade other tissues. "This identified 160 significant non-coding elements, including the TERT promoter, a well-known non-coding driver element, as well as elements associated with known cancer genes and regulatory genes (e.g., PAX5, TOX3, PCF11, MAPRE3)." (PMID 29354286, 2018). "The genes GCK, MAPRE3, and MAPRE2 hold promise for guiding therapeutic strategies for organ-specific cancers." (PMID 38971308, 2024). "MAPRE3 (also known as EB3 or EBF3) codes for a microtubule end-binding protein that stabilizes focal adhesions and has been demonstrated to trigger apoptosis in cancer types other than those analyzed here." (PMID 28423600, 2017). "Genomic alterations of MAPRE3 (encoding EB3) and its expression by RNA-seq did not correlate with overall survival outcomes of cancer patients across The Cancer Genome Atlas, suggesting that EB3 itself is not a major driver of disease progression." (PMID 32665556, 2020).
tumor (3 papers, 2017 to 2024). "While CCND1 and FOXI1 were enriched in the nuclei, GPNMB showed a homogeneous and moderate/strong expression within the cytoplasmic compartment of the chRCC tumor cells, and MAPRE3 protein showed a predominant membranous expression pattern in RO." (PMID 38703764, 2024). "Among the top five growth-suppressing genes tested, STARD8 and DUSP6, a commonly known tumor suppressor, arrested cells in G1/G0-phase, while MAPRE3, RPS6KA2 and EMD induced apoptosis." (PMID 28423600, 2017).
MAPRE3 also shares sentences with these, for which no sentence is quoted: neuroblastoma (4 papers); Ebola virus disease (3); viral diseases (3); (HCMV) infection (2); tauopathy (2); Alzheimer disease (1); amyotrophic lateral sclerosis (1); aortic aneurysm (1); cervical cancer (1); colon carcinoma (1); frontotemporal dementia (1); infection (1); infertile (1); prostate carcinoma (1); renal cell carcinoma (1); temporal lobe epilepsy (1).